DDAH2 (DDAH family member 2, ADMA-independent)
Diseases named in the same sentence as DDAH2 in open-access papers (continued):
Sharing a sentence is not in itself a finding about the gene and the disease.
lung adenocarcinoma (6 papers, 2016 to 2023). A carcinoma that arises from the lung and is characterized by the presence of malignant glandular epithelial cells. "Our data indicate that expression of DDAH2 is associated with invasiveness of lung adenocarcinoma via tumor angiogenesis." (PMID 26515557, 2016). "One of the noteworthy findings of this study was that DDAH2 is expressed in cancer-associated fibroblasts (CAF) of lung adenocarcinoma." (PMID 26515557, 2016). "DDAH2, in turn, has been implicated in angiogenesis in lung adenocarcinoma." (PMID 32121248, 2020). "In our previous studies, we found that IGBP1, OCIAD2 and DDAH2 showed high expression in lung adenocarcinoma and their expression appeared to be epigenetically regulated." (PMID 30899432, 2019). "A more recent study in 2016 identified increased expression of DDAH2 in the stroma fibroblasts of lung adenocarcinomas, where tumors with high stromal DDAH2 expression had a poorer prognosis." (PMID 31993367, 2019). "In surgically resected specimens, high expression of DDAH2 in stroma of invasive lung adenocarcinoma correlated with stronger eNOS expression in the vascular endothelium of the malignant tissue." (PMID 31993367, 2019). "By immunoprecipitation, we then isolated the recognized antigen in frozen human lung adenocarcinoma tissue, and identified this using LC-MS/MS as DDAH2." (PMID 26515557, 2016). "We initially examined expression of DDAH2 in lung adenocarcinomas using immunohistochemistry and found a significant difference in the proportion of DDAH2-positive cases between MIA, invasive adenocarcinoma, and preinvasive lesions." (PMID 26515557, 2016). "The therapeutic potential of DDAH2 as target for inhibition of tumor angiogenesis in lung adenocarcinoma, complementary to conventional antiangiogenic therapy, merits to be explored." (PMID 26515557, 2016). "It is of considerable interest that DDAH2 accelerates the progression of lung adenocarcinoma whereas it works as a preventive factor against cardiovascular and chronic kidney diseases." (PMID 26515557, 2016). "We demonstrate that DDAH2 is a marker of tumor angiogenesis and is expressed in lung adenocarcinoma at an early stage." (PMID 26515557, 2016). "We developed a monoclonal antibody specifically reacting with stroma of lung adenocarcinoma, and identified the recognized antigen as DDAH2." (PMID 26515557, 2016). "One reacted characteristically with the stromal region of human lung adenocarcinoma, and the antigen was identified as dimethylarginine dimethylaminohydrolase 2 (DDAH2) by LC/MS-MS analysis." (PMID 26515557, 2016). "Taken together, our findings suggest that DDAH2 promotes tumor angiogenesis in lung adenocarcinoma by increasing the production of NO." (PMID 26515557, 2016). "Using immunohistochemistry, we then examined expression of DDAH2 on 133 cases of surgically resected lung adenocarcinoma." (PMID 26515557, 2016). "DDAH2 was reported to be involved in the invasion of lung adenocarcinoma by promoting angiogenesis." (PMID 36765702, 2023). "In conclusion, DDAH2 is expressed in CAF in early stage lung adenocarcinoma and might play an important role in tumor invasion by promoting tumor angiogenesis through an increase of NO production." (PMID 26515557, 2016). "We show that DDAH2 plays an important role in tumor angiogenesis in lung adenocarcinoma." (PMID 26515557, 2016). "We hypothesized that DDAH2 contributes to lung adenocarcinoma invasion through promotion of tumor angiogenesis." (PMID 26515557, 2016). "We hypothesized that DDAH2 contributes to lung adenocarcinoma invasion through tumor angiogenesis via NO production and expected that eNOS expression might increase upon stimulation by DDAH2." (PMID 26515557, 2016). "Inhibition of DDAH2 activity in lung adenocarcinoma may therefore become a promising therapeutic strategy complementing conventional antiangiogenic therapy." (PMID 26515557, 2016).
lung adenocarcinoma (continued). "We also found that DDAH2 derived from CAF promotes tumor angiogenesis in lung adenocarcinoma." (PMID 26515557, 2016). "This suggests that DDAH2 might be a novel prognostic indicator in lung adenocarcinoma and useful for the detection of early invasive adenocarcinoma such as MIA." (PMID 26515557, 2016). "Possible functional relationships between VEGF and DDAH2 in lung adenocarcinoma need to be studied." (PMID 26515557, 2016). "Furthermore, DDAH2 has been shown to promote angiogenesis via upregulating the expression of the endothelial isoform of NOS, as demonstrated in lung adenocarcinoma cell lines, and to be associated with aggressive lung cancer phenotype as well as poor patient survival." (PMID 32932854, 2020). "DDAH2 expression might be a prognostic factor in lung adenocarcinoma." (PMID 26515557, 2016). "We next examined whether DDAH2 might be a prognostic factor for lung adenocarcinoma." (PMID 26515557, 2016). "We observed diffuse staining of DDAH2 in cancer stroma and detected expression of DDAH2 mRNA in CAF of lung adenocarcinoma by in situ hybridization." (PMID 26515557, 2016). "The stroma of lung adenocarcinoma showed diffuse staining for DDAH2, whereas tumor cells themselves were not stained." (PMID 26515557, 2016). "Because most lung adenocarcinomas develop in a stepwise manner from AAH to AIS, and then from MIA to invasive adenocarcinoma, it has been suggested that DDAH2 might play an important role in the progression of lung adenocarcinoma, especially in the early phases of tumor invasion." (PMID 26515557, 2016).
pulmonary hypertension (6 papers, 2010 to 2023). Increased pressure within the pulmonary circulation due to lung or heart disorder. "Although impairment or decreased expression of DDAH2 has been reported in several diseases such as chronic kidney disease, pulmonary hypertension, and cardiovascular disease, the association of DDAH2 with malignancy has received less attention." (PMID 26515557, 2016). "Common single nucleotide polymorphisms in the DDAH1 and DDAH2 genes predispose humans to high ADMA levels and hypoxia-induced pulmonary arterial hypertension." (PMID 37629272, 2023). "Moreover, expression of DDAH2 was also found to be reduced when comparing lung tissue from pulmonary hypertensive rats and idiopathic pulmonary arterial hypertension (IPAH) patients to corresponding normal lung tissue." (PMID 20504321, 2010). "Therefore, we selected 16 single nucleotide polymorphisms in NOS3, DDAH1, DDAH2, AGXT2, ARG1, ARG2, and PRMT1 genes and studied their associations with dimethylarginine concentrations and the incidence of high-altitude pulmonary hypertension as well as acclimatization to high altitude." (PMID 34945057, 2021). "Reduced DDAH2 protein and mRNA, paralleled by elevated ADMA, were observed in patients with idiopathic pulmonary arterial hypertension and in pulmonary hypertensive rats." (PMID 34356605, 2021). "In WT mice, downregulation of DDAH1 may be the major cause for elevation of ADMA in hypoxia, while in Ddah1−/− mice, DDAH2 protein is upregulated, limiting further dysregulation of ADMA-related pathways and, by this, pulmonary hypertension and cardiac hypertrophy in hypoxia." (PMID 33281630, 2020).
type 2 diabetes (5 papers, 2010 to 2025). "Examining data from the DIAGRAM+ meta-analysis for genes involved in endothelial function led us to the identification of a variant (rs9267551) in the DDAH2 gene nominally associated with type 2 diabetes (P = 3×10−5)." (PMID 22558392, 2012). "To find further support for the role of DDAH2 in the pathogenesis of type 2 diabetes, we examined the functional impact of this polymorphism in human endothelial cells." (PMID 22558392, 2012). "This study found genetic variation in the DDAH1 and DDAH2 genes to be significantly associated with serum ADMA levels in participants with type 2 diabetes." (PMID 20209122, 2010). "A functional polymorphism of the DDAH2 gene may confer increased risk for type 2 diabetes by affecting insulin sensitivity throughout increased ADMA levels." (PMID 22558392, 2012). "In conclusion, our data indicate that a functional polymorphism in the DDAH2 gene may confer increased risk of type 2 diabetes by affecting insulin sensitivity due to an increase in circulating ADMA levels." (PMID 22558392, 2012). "In view of the important role of ADMA in regulating endothelium-dependent vasodilation and, thereby, insulin sensitivity, we hypothesized that polymorphisms in the DDAH2 gene, potentially altering its expression or activity, may be associated with type 2 diabetes." (PMID 22558392, 2012). "The antagonistic pleiotropic impact of DDAH2 expression level on disorders such as multiple sclerosis and type 2 diabetes indicate finding an optimal level is important in regulating the expression of DDAH2 for therapeutic purposes." (PMID 40864748, 2025). "We sought to determine whether serum ADMA levels in type 2 diabetes are influenced by common polymorphisms in the DDAH1 and DDAH2 genes." (PMID 20209122, 2010). "In conclusion, genetic variation in DDAH1 and DDAH2 genes was found to be strongly and significantly associated with serum ADMA levels in patients with type 2 diabetes, especially in those without retinopathy." (PMID 20209122, 2010).
Coronary Artery Disease (4 papers, 2014 to 2025). "This study aimed to analyze the single nucleotide polymorphism (SNP) of the NOS3 and DDAH2 genes and to identify their association with the risk of coronary artery disease (CAD)." (PMID 40144407, 2025). "The functional variant rs9267551 C, in the promoter region of DDAH2, has been linked to increased DDAH2 expression, and lower ADMA plasma levels, and was associated with lower risk of coronary artery disease in large-scale genome-wide association studies (GWAS) performed in the general population." (PMID 31409409, 2019).
prostate carcinoma (4 papers, 2016 to 2020). A carcinoma that arises from epithelial cells of the prostate gland. "Moreover, the expression of DDAH2 only tended to weakly correlate with NOS2 in tumors, although in prostatic cancer cell lines, its expression was accompanied by the upregulation of iNOS and VEGF-A." (PMID 32872669, 2020). "DDAH2 protein expression has been less extensively studied in cancer, but an upregulation has been reported in prostate cancer cell lines as well as the malignant stroma (but not tumor cells) of non-small-cell lung cancer tissue." (PMID 31993367, 2019).
schizophrenia (4 papers, 2022 to 2025). A major psychotic disorder characterized by abnormalities in the perception or expression of reality. "Reduced methylation near the transcription start site of DDAH2 in the frontal cortex of patients with schizophrenia has been associated with increased gene expression." (PMID 41017816, 2025). "SNPs in DDAH1 and DDAH2 are associated with schizophrenia, bipolar disorder, depression, anxiety, and alcohol dependence, as well as broader traits such as neuroticism, guilt feelings, and sleep quality parameters." (PMID 41017816, 2025). "Specifically, we evaluated evidence of DDAH1 and DDAH2 involvement in regulating processes associated with major psychotic disorders, schizophrenia, and bipolar disorder." (PMID 36233204, 2022). "For DDAH2 expression, upregulation is reported in association with schizophrenia patient-specific methylations and promoter region SNPs." (PMID 36233204, 2022). "However, tissue-specific differences cannot be excluded, as conversely, increased methylation of DDAH2’s regulatory regions has been noted in blood-derived cells of patients with schizophrenia, with this methylation status being linked to suicide attempts." (PMID 41017816, 2025). "DDAH2 gene variants are associated with schizophrenia and bipolar disorder susceptibility." (PMID 36233204, 2022). "In the meantime, we did not observe any over-represented motives in the promoters of DDAH2 co-expressed genes in patients with schizophrenia." (PMID 36233204, 2022). "In schizophrenia patients, the DDAH2 gene is aberrantly methylated in both the prefrontal cortex and blood, and DDAH2 brain mRNA levels are significantly increased." (PMID 36233204, 2022). "Many of these genes have been previously linked to brain-related disorders, including Alzheimer’s disease (WDR12, AGFG2, and CDK5RAP3), schizophrenia (SRA1, WDR55, CORO7, DDAH2, PCDHA8), autism spectrum disorder (MAPK3, PCDHA13), and major depressive disorder (ZMAT2 and ITIH4)." (PMID 39269986, 2024). "Other studies have also shown that DDAH2 mRNA levels were significantly elevated in brain tissue in schizophrenia, although the brain region was not specified in this study." (PMID 36233204, 2022). "However, in contrast to non-psychiatric controls and schizophrenia, many other enriched promoter motifs in genes co-expressed with DDAH2 are found in patients with bipolar disorder samples." (PMID 36233204, 2022). "The dataset GSE112523 combines data from subjects with schizophrenia, bipolar affective disorder, and non-psychiatric controls; thus, it was further analyzed to compare DDAH1 and DDAH2 co-expressed gene sets in these psychiatric disorders." (PMID 36233204, 2022).
atherosclerosis (3 papers, 2014 to 2022). A disease characterized by the build-up of fatty material and calcium deposition in the arterial wall resulting in partial or complete occlusion of the arterial lumen. "Homocysteine disrupts EPCs function via inducing the hypermethylation of DDAH2 promoter, suggesting a key role of epigenetic mechanism in the progression of atherosclerosis." (PMID 24934151, 2014). "The present study provides new evidence for the role of aberrant DDAH2 methylation in modulating EPCs function and suggests a new epigenetic target in the treatment of atherosclerosis." (PMID 24934151, 2014). "In addition, a recent study suggested that hyperuricemia promotes atherosclerosis by disturbing the balance of the asymmetric dimethylarginine (ADMA)/dimethylarginine dimethylaminotransferase-2 (ADMA/DDAH-2) axis." (PMID 36046689, 2022). "Consequently, DDAH2 is recognized as a protective factor of endothelial function and a potential therapeutic target for cardiovascular diseases such as atherosclerosis, diabetes mellitus and aging." (PMID 24934151, 2014). "DDAH2 predominates in tissues that express endothelial NOS and the impairment of DDAH2 activity and/or expression rather than DDAH1 appears to be responsible for the elevation of plasma ADMA in endothelial cells of atherosclerosis." (PMID 24934151, 2014).
bipolar disorder (3 papers, 2022 to 2025). A disorder of the brain that causes unusual shifts in mood, energy, activity levels and the ability to carry out day-to-day tasks. "Increased DDAH2 expression has been observed in the prefrontal cortex of patients with bipolar disorder, with functional associations with apoptosis." (PMID 41017816, 2025). "Slight upregulation of DDAH2 was identified in the tissue samples from patients with bipolar disorder compared to the control group in the GSE112523 dataset." (PMID 36233204, 2022). "While, in genes co-expressed with DDAH2 in the prefrontal cortex of patients with bipolar disorder, several protein-binding patterns are significantly over-represented." (PMID 36233204, 2022). "DDAH2 expression upregulation has also been described in the prefrontal cortex of patients with bipolar disorder." (PMID 36233204, 2022). "Over-representation may thus link prefrontal DDAH2 functionality with sleep disturbance, a core symptom of bipolar disorder." (PMID 36233204, 2022). "The co-expression of DDAH1 and DDAH2 with the genes annotated with these terms was identified in dorsolateral prefrontal cortex samples in non-psychiatric controls but was lost both in schizophrenic and bipolar disorder patients." (PMID 36233204, 2022). "The C2H2 zinc finger MZF-1 binding pattern is over-represented in DDAH2 co-expressed genes in non-psychiatric subjects and patients with bipolar disorder, but in schizophrenic patients, this association is lost." (PMID 36233204, 2022).
chronic kidney disease (3 papers, 2014 to 2016). Impairment of the renal function secondary to chronic kidney damage persisting for three or more months. "Some variants of the DDAH2 gene were reported to be associated with chronic kidney disease and insulin sensitivity." (PMID 24603538, 2014).
ovarian carcinoma (3 papers, 2016 to 2023). A malignant neoplasm originating from the surface ovarian epithelium. "PRMT5, PRMT1, DDAH1, DDAH2, NOS2, ARG1, and ARG2 were all found to be up-regulated in the stage I/II or stage III/IV ovarian cancer tissues compared to normal tissues." (PMID 37684587, 2023). "These genes include stratifin (SFN), immunoglobulin binding protein 1 (IGBP1), ovarian carcinoma immunoreactive antigen domain 2 (OCIAD2), and dimethylarginine dimethylaminohydrolase 2 (DDAH2)." (PMID 30899432, 2019). "Notably, gene clusters of PRMT1/PRMT5 and DDAH1/DDAH2/ARG2 persisted, while other gene tree relationships and expression significances differed between the two comparisons: normal tissue versus stage I/II ovarian cancer and stage I/II versus stage III/IV ovarian cancer." (PMID 37684587, 2023).
viral infection (3 papers, 2010 to 2025). "It is also reported that DDAH2 translocates to mitochondria during viral infections, where it promotes mitochondrial fission and modulates the innate immune response." (PMID 40864748, 2025). "In line with this concept, the nitric oxide (NO) producer dimethylarginine dimethylaminohydrolase 2 (DDAH2) inhibits MAVS activity during viral infection by promoting mitochondrial fission." (PMID 34386501, 2021). "NO produced by DDAH2 in response to viral infection stimulates the phosphorylation of the dynamin-related protein-1 (DRP-1) and promotes mitochondrial fission." (PMID 34386501, 2021).
autoimmune disease (2 papers, 2011 to 2021). A disorder resulting from loss of function or tissue destruction of an organ or multiple organs, arising from humoral or cellular immune responses of the individual to their own tissue constituents. "The DDAH-2 gene is located on chromosome 6 (6p21.3) in a region containing various genes involved in inflammatory processes linked with the autoimmune disease susceptibility." (PMID 21408057, 2011). "Some of these novel risk genes such as DDAH2 and HLA-DMA have been reported to be associated with the autoimmune diseases, including type I diabetes, rheumatoid arthritis, and systemic lupus erythematosus." (PMID 34872583, 2021).
glioma (2 papers, 2016 to 2019). A benign or malignant brain and spinal cord tumor that arises from glial cells (astrocytes, oligodendrocytes, ependymal cells). "An increase in DDAH2 mRNA expression is further observed in glioblastoma, brain lower grade glioma and liver cancer samples, whilst a decrease is observed in cervical cancer samples relative to normal tissue." (PMID 31993367, 2019).
hyperhomocysteinemia (2 papers, 2014 to 2019). A serious metabolic condition caused by mutations in the MTHFR gene, medications, or nutritional deficiency. "Although previous studies had already reported that hyperhomocysteinemia mediates vascular dysfunction by increasing ADMA and down-regulating DDAH2, the implication of PON1 needed to be explained." (PMID 31817387, 2019).
idiopathic pulmonary arterial hypertension (2 papers, 2010 to 2014). A sporadic form of pulmonary arterial hypertension (PAH) characterized by elevated pulmonary arterial resistance leading to right heart failure. "The underlying mechanism is a decreased expression and activity of DDAH-2 which was shown in lungs from patients with idiopathic pulmonary arterial hypertension (IPAH) as well as in lungs of Monocrotaline-treated rats." (PMID 24719871, 2014).